CRP (C-reactive protein)
Diseases named in the same sentence as CRP in open-access papers (continued):
Sharing a sentence is not in itself a finding about the gene and the disease.
Sepsis (continued). "PCT and IL-6 are also often examined in cases wherein a more severe infection, such as sepsis, is suspected because these markers are reportedly better in detecting sepsis than CRP." (PMID 33211747, 2020). "The novel biomarkers TNFR1 and TNFR2 performed similarly to NGAL and CRP in identifying sepsis patients." (PMID 32948801, 2020). "Scr (P < .001), WBC (P = .019), and CRP (P < .001) were increased, while albumin (P < .001) was decreased in sepsis patients compared with healthy controls." (PMID 32309886, 2020). "We explored the effects of administering dexmedetomidine on the levels of C-reactive protein (CRP) and procalcitonin, and thus on inflammation, in patients with sepsis enrolled in a randomized clinical trial." (PMID 32778146, 2020). "Data from small study groups suggest a better correlation with severity and mortality from sepsis compared to CRP." (PMID 33419284, 2020). "In recent years, great progress has been made in searching for biomarkers of sepsis, including CALCA (also known as PCT), C-reactive protein, and interleukin-6 which have been found to be biomarkers of sepsis." (PMID 32596378, 2020). "Our proteomics data revealed that the plasma concentration of AACT followed a similar trend as CRP and other APPs, with a notable increase in abundance upon sepsis, reverting to baseline at T4." (PMID 33519818, 2020). "The Z score mean values of nCD64% in both the proven sepsis and clinical sepsis groups were 4.6698 (1.185-5.79) and 3.73454 (-1.675-5.894), respectively, while the hs-CRP Z score mean values were 2.84013 (-0.423-8.118) and 1.34492 (-0.423-9.301), respectively." (PMID 32832553, 2020). "The results of the present study showed a significant increase (<0.001) in IL-6 and CRP concentrations among culture proven sepsis and clinical sepsis cases compared to controls." (PMID 33233806, 2020). "Some biomarkers like procalcitonin and C-reactive protein are used for diagnosis and to access sepsis prognosis and they can help in clinical decision-making, but none has sufficient specificity or sensitivity to be routinely employed in clinical practice." (PMID 32284068, 2020). "Nevertheless, we were able to indicate some parameters that correlated with the development of NEC in patients with PDA (such as suspected sepsis, CRP level, platelet count)." (PMID 32411635, 2020). "So, many sepsis markers, like C-reactive protein (CRP), procalcitonin (PCT), and interleukin-6 (IL-6), are emerging to improve its diagnosis." (PMID 33061986, 2020). "Univariate regression analysis results indicate significant correlation to PIICS development by all of the following: age, male sex, SOFA and APACHEII score, sepsis, initial CRP, albumin, lymphocyte count, Hb and creatinine on admission." (PMID 32824569, 2020). "They found that suPAR outperformed CRP for the differentiation of sepsis and SIRS, but was itself outperformed by PCT (AUCs for suPAR, CRP and PCT were 0.817, 0.681 and 0.892, respectively)." (PMID 32164268, 2020). "Accordingly, it would still be likely to find a subgroup where CRP would be predictive of sepsis or the related complications." (PMID 33198109, 2020). "Therefore, we can conclude that advanced age, particularly over 80 years, increase in inflammatory parameters, namely CRP and white blood cells as well as a diagnosis of sepsis are independent risk factors for death and could be used as predictive markers of CDI poor outcome." (PMID 32895405, 2020). "TNFR1 and TNFR2 performed similarly to NGAL and CRP in identifying sepsis patients, but they performed better than CRP in predicting 30-day mortality in this ICU cohort." (PMID 32948801, 2020). "This manifests with high D-dimer, high C-reactive protein levels, anti-phospholipid antibodies and sepsis-induced coagulopathy, and is likely to increase mortality." (PMID 33357240, 2020). "Many previous studies have suggested the utility of the CRP level as an outcome predictor in critically ill patients with sepsis." (PMID 32430043, 2020).
Sepsis (continued). "Among the routine sepsis screen tests and other categorical parameters, Age, elevated CRP, haemoglobin, I/T ratio, platelet count were significantly different between culture positive sepsis and no sepsis group." (PMID 32157117, 2020). "The presented LFAs were designed to detect the sepsis biomarkers CRP and IL-6 simultaneously on one test line, by using two different QDs as labels." (PMID 32912236, 2020). "The prognostic value of CRP in pediatric patients with sepsis needs further investigation, especially in the aspect of the top level of CRP within 1 week after PICU admission or the changes of CRP during hospitalization." (PMID 32410872, 2020). "The areas under the receiver operating characteristic (AUROC) curves of PCT and CRP for predicting pathogen-positive results of REBA Sepsis-ID were 0.72 and 0.69, respectively." (PMID 32850901, 2020). "A 4-variable model including medical admission, sepsis diagnosis, simplified acute physiologic score II and basal serum C-reactive protein (CRP) accurately classified each phenotype (area under curve 0.82; 95% CI, 0.79–0.86)." (PMID 32358385, 2020). "The level of IL-6 usually increases earlier than that of PCT and CRP, making it a potential biomarker for early detection among sepsis patients." (PMID 33198109, 2020). "Historically, a plasma CRP level of 50 mg/L or more was highly suggestive of sepsis (sensitivity 98.5%, specificity 75%)." (PMID 33266250, 2020). "The feasibility of POCT for sepsis-related biomarkers has clearly been demonstrated by the existing commercially available assays that are routinely used for biomarkers such as CRP, lactate and PCT." (PMID 32164268, 2020). "In this work, three inflammatory cytokines with different action, IL-8, IL-12/23 p40, and IL-6, and CRP were taken to indicate inflammatory processes or sepsis." (PMID 32842482, 2020). "We also conducted an updated meta-analysis in 2019 with 14 studies and 2471 patients comparing the accuracy of neutrophil CD64, procalcitonin, and CRP in detecting adult patients with sepsis." (PMID 33198109, 2020). "Procalcitonin (PCT) and C-reactive protein (CRP) have been most widely used, but even they have limited ability to distinguish sepsis from other inflammatory conditions or to predict outcomes." (PMID 32284068, 2020). "The CRP/albumin ratio has been already identified as a prognostic biomarker to assess outcomes in patients with sepsis, cancer, and chronic inflammatory diseases." (PMID 32344777, 2020). "So, PCT is superior to CRP in the early diagnosis of neonatal sepsis, detecting sepsis severity and evaluating the antibiotic treatment response." (PMID 33061986, 2020). "Recent studies focus on the identifying of biomarkers that are helpful for the early diagnosis of sepsis, such as CRP and PCT." (PMID 32188465, 2020). "Younger adults expressed fibrinogen, and von Willebrand factor in response to sepsis while CRP, LBP, and A1ACT showed lower concentrations in older adults who developed severe sepsis but Apo M in older adults was associated with increased mortality." (PMID 32636717, 2020). "An earlier study by Zeng and co-workers measured suPAR, PCT and CRP in patients with sepsis and SIRS and a healthy control group." (PMID 32164268, 2020). "Many other clinical trials investigated early diagnosis of sepsis and septic shock using other markers, like: CRP, ESR, procalcitonin, and various interleukins, but none of them positively identified a certain marker for accurate early diagnosis." (PMID 33374939, 2020). "The aim of this study was to evaluate the diagnostic and prognostic value of IL-6 and sTREM-1 in the course of SIRS and sepsis in children with reference to routinely used CRP and PCT." (PMID 32655314, 2020). "C-reactive protein (CRP) is an acute phase response protein, markedly elevated during sepsis in humans." (PMID 32110278, 2020).
Sepsis (continued). "Pairwise comparison of all ROC curves evaluating the differences between AUCs showed that presepsin is significantly better than the SOFA score (Diff AUC = 0.075, p < 0.01) but similar to CRP (Diff AUC = 0.059, p = 0.123) in predicting sepsis severity." (PMID 33374939, 2020). "We reviewed six promising biomarkers for detecting sepsis and systemic infection, including C-reactive protein (CRP), procalcitonin (PCT), interleukin-6 (IL-6), CD64, presepsin, and sTREM-1." (PMID 33198109, 2020). "In particular, D-Dimer is frequently elevated in patients with an inflammatory background (i.e. infectious diseases, sepsis, rheumatic diseases) characterized by elevated unspecific inflammatory markers such as c-reactive protein (CRP)." (PMID 32215782, 2020). "We found that lnc‐MALAT1/miR‐125a axis was positively associated with APACHE II score, SOFA score, Scr, CRP, TNF‐α, IL‐1β, IL‐6, and IL‐8, while negatively associated with albumin in sepsis patients." (PMID 32309886, 2020). "This implies that a positive CRP will correctly diagnose about 9 of 10 neonates suspected with sepsis, and among them, seven will have a positive blood culture." (PMID 32238170, 2020). "As these cases demonstrate, clinical risk factors for sepsis should be taken into consideration before initiating tocilizumab treatment since signs and symptoms of sepsis like fever and CRP values can be masked." (PMID 32086584, 2020). "Various biomarkers are currently used for the early confirmation of infection and tissue damage in sepsis: C-reactive protein, leukocyte level, lactate level, and procalcitonin (PCT)." (PMID 32952850, 2020). "In such cases, the values of CRP during systemic inflammatory response syndrome and sepsis tend to be much higher—typically greater than 150 mg/L33—than in VTE." (PMID 32879351, 2020). "As the blood test revealed elevated white blood cell count (27,800/μL) and C reactive protein level (CRP, 8.89 mg/dL), sepsis was suspected, and intravenous administration of cefepime was initiated." (PMID 32282733, 2020). "A slower and less obvious MBL response to infection or surgical trauma compared with other acute phase reactants, as C-reactive protein, and variable responses in sepsis have been reported." (PMID 32817747, 2020). "The two biomarkers that have been most widely studied and used in patients with sepsis are the short pentraxin C-reactive protein (CRP), and procalcitonin (PCT), the prehormone of calcitonin." (PMID 33301518, 2020). "The CRP to albumin (CRP/Alb) ratio has recently been considered a more useful indicator of sepsis than CRP or albumin alone." (PMID 33324592, 2020). "The elevated micro- Erythrocyte sedimentation level was seen in relation to sepsis types and C-reactive protein." (PMID 32788752, 2020). "The most commonly used biomarkers of inflammation were CRP and leucocytes, while, for sepsis screening, besides these two, serum procalcitonin and presepsin are useful." (PMID 32731610, 2020). "The most commonly used biomarkers for identifying sepsis are lactic acid and C-reactive protein (CRP)." (PMID 32153412, 2020). "The activation of the systemic inflammatory reaction in sepsis was monitored with a C-reactive protein (CRP), procalcitonin (PCT), and white blood cell count (WBC)." (PMID 32801997, 2020). "The aim of this study was to evaluate the diagnostic and prognostic value of IL-6 and sTREM-1 in the course of acute inflammation among children, especially taking into consideration SIRS and sepsis with reference to routinely used CRP and PCT." (PMID 32655314, 2020). "Baseline characteristics (pH, lactate, creatinine and CRP) of MALA patients were compared with patients with suspected sepsis induced lactic acidosis." (PMID 32960426, 2020). "This study defines the optimal cut-off values for IL-6 and CRP in the first five days of serial measurements using large number of culture-proven sepsis cases." (PMID 33233806, 2020).
Sepsis (continued). "In this study, we also analyzed CRP concentrations as a possible predictive biomarker for true-positive REBA Sepsis-ID and BC results." (PMID 32850901, 2020). "Previous studies showed a correlation between the PCT and the CRP levels in the proved sepsis group after 12–24 h of admission in contrast to IL-6, which had a very short half-life and became undetectable 24 hours after the onset of infection." (PMID 33061986, 2020). "Systemic diseases characterized by elevated levels of C-reactive protein (CRP), such as sepsis or systemic inflammatory response syndrome, are usually associated with hardly controllable haemodynamic instability." (PMID 32983135, 2020). "While MPV in this study was the least sensitive platelet parameter, but it was still more sensitive than CRP, which is the most commonly used inflammatory marker to be assessed in children with sepsis." (PMID 32814554, 2020). "SIRT1 negatively correlated with Scr (r=-0.236), WBC (r=-0.202), and CRP (r=-0.405) and positively correlated with albumin (r=0.416) in sepsis patients." (PMID 33263643, 2020). "In these groups, similar concentrations of CRP were observed in patients with sepsis and septic shock." (PMID 32952850, 2020). "Comparing CRP as a standard sepsis biomarker being widely used in worldwide NICUs, it is available with reasonable turnaround time, high specificity, and lower financial cost comparable to the new biomarkers." (PMID 33204274, 2020). "Transcriptomic upregulation of CRP is induced by increased levels of interleukin-6, which is commonly elevated in the early phases of sepsis." (PMID 32932765, 2020). "We analyzed data derived from a randomized clinical trial and found that the administration of dexmedetomidine to patients with sepsis on ventilators improved CRP and PCT levels during the first 14 days in the ICU." (PMID 32778146, 2020). "Group D showed significantly higher CRP levels (D: 23.1 ± 12.9 mg/dl vs. S: 10.9 ± 11.1 mg/dl; p = 0.01) and signs of sepsis at admission (D: n = 13/17, 76.5% vs. S: n = 38/180, 21.1%; p ≤ 0.01)." (PMID 32728904, 2020). "Existing biomarkers for sepsis, such as c-reactive protein (CRP), procalcitonin (PCT), and IL-6, have limited specificity and sensitivity." (PMID 32214905, 2020). "NEC patients had lower Apgar score (1′), more congenital malformations, more suspected sepsis, less hypotension, higher minimum platelet count and higher CRP-values during the week before NEC (P < 0.05, respectively)." (PMID 32411635, 2020). "The median levels of IL-6, PCT, and CRP were statistically significantly higher in children with sepsis compared to children with SIRS (118 pg/ml, 2.55 ng/ml, and 48 mg/l vs. 52 pg/ml, 1.0 ng/ml, and 33.5 mg/l, respectively)." (PMID 32655314, 2020). "Patients with sepsis ranged from 17.1 to 64.3% and the mean or median C-reactive protein reported ranging from 6.6 to 26.5 mg/dL." (PMID 32933198, 2020). "Recent several studies have included many sepsis markers, like C-reactive protein (CRP), procalcitonin (PCT), and interleukin-6 (IL-6) to improve sepsis diagnosis." (PMID 33061986, 2020). "Some of the studies have also investigated the use of combination of VCS parameters along with other parameters of sepsis screen, CRP and IL-63,6." (PMID 32157117, 2020). "Pairwise comparison of the ROCs proved that the value of presepsin in predicting sepsis mortality is overall higher than all the other parameters, including CRP (Diff AUC = 0.113, p = 0.0021) and SOFA (Diff AUC = 0.086, p = 0.0072)." (PMID 33374939, 2020). "The analysis carried out on couples of markers (PCT and sCD14-ST; PCT and CRP; CRP and sCD14-ST) and on the three markers together, resulted in increased levels in almost every sepsis case and normal values in almost every control case (data not shown)." (PMID 33092081, 2020). "Otherwise, CRP is a well-known parameter for diagnosis of sepsis or assessment of predictor of successful antibiotic therapy." (PMID 32410872, 2020).
Sepsis (continued). "They did not provide, however, a comparison between MDW with other available biomarkers of sepsis as PCT or C-reactive Protein (CRP)." (PMID 31923207, 2020). "The limited data from the literature regarding sepsis prognosis in children indicate a higher PCT value as compared to CRP and sTREM-1." (PMID 32655314, 2020). "Mean serum albumin and Apo-A1 concentrations were significantly lower in dogs with sepsis compared to healthy ones, while mean serum CRP concentrations were above the reference interval in the entire population of septic dogs." (PMID 32478112, 2020). "There is an abundant literature on CRP as a sepsis marker whereas the literature on CRP in haematological cancer patients is much sparser." (PMID 32209087, 2020). "Although significant, CRP concentration showed a poor performance in predicting true-positive REBA sepsis-ID and BC results." (PMID 32850901, 2020). "Clinical signs and/or laboratory results indicative of sepsis were present in 80 (83%); 69 (72%) had clinical signs; 34 (35%) had an elevated CRP and 23 (24%) had an abnormal white cell count." (PMID 31978082, 2020). "We then examined the serum levels of inflammatory cytokine TNF-α, IL-6, IL-1β, and IL-10, and the clinical markers of acute systemic inflammation MCP-1 and CRP by ELISA in LPS-induced sepsis model." (PMID 32457606, 2020). "Around 80% (92/116) of consultants estimated that 75% of patients have a CRP test performed to support a diagnosis of sepsis." (PMID 33114715, 2020). "The use of biomarkers has been alluded to in the definitions of sepsis; both C-reactive protein (CRP) and procalcitonin (PCT) are inflammatory parameters included in the 2001 SIRS criteria." (PMID 32164268, 2020). "C-reactive protein was chosen as parameter for the most severe stage of sepsis since it reflects the inflammatory process and is widely used in clinical routine." (PMID 33083117, 2020). "Many clinicians have studied the usefulness of blood biomarkers such as CRP and procalcitonin for early assessment of sepsis." (PMID 32075629, 2020). "Based on the ROC curves, the diagnostic value of IL-6, sTREM-1, PCT, and CRP in an acute inflammation diagnosis (especially in SIRS and sepsis) and the prognostic value of febrile disease course were evaluated." (PMID 32655314, 2020). "It was evident for us during the study course that both nCD64 and presepsin rise in the early stages of sepsis process, being earlier than CRP, and decrease more rapidly and dramatically with proper treatment and clinical improvement." (PMID 33204274, 2020). "To date, the use of PCT and CRP in predicting sepsis or sepsis-related mortality or other adverse outcomes has been evaluated exclusively in infectious or septic patients." (PMID 32881963, 2020). "In the present study, dogs with sepsis showed increased serum CRP concentrations and, at the same time, significantly lower serum Apo-A1 concentrations compared to a group of healthy dogs." (PMID 32478112, 2020). "The classical laboratory parameters including WBC, CRP, and cytokines are widely used in sepsis diagnostics." (PMID 32948040, 2020). "With the chosen cut-off values for sepsis in this study, CRP had higher sensitivity and specificity than other biomarkers for identifying sepsis patients in this ICU cohort." (PMID 32948801, 2020). "The 93 suspected septic episodes were classified as sepsis or non-sepsis group based on clinical presentation, CRP, time to positivity of blood culture (less than 24 hours), and the presence of a single organism in the blood culture." (PMID 32750089, 2020). "Several therapeutic strategies for sepsis aim to modulate inflammatory responses such as low-dose glucocorticoids, C-reactive protein inhibitors, TNF-α and IL-1β receptor antagonists, recombinant IL-17, and PD-1 immunotherapy, etc.." (PMID 32153412, 2020). "In culture proven sepsis cases, the highest concentration of CRP was observed in the second day measurement (CRP2)." (PMID 33233806, 2020).